BPTF (bromodomain PHD finger transcription factor)
Description:
Regulatory subunit of the ATP-dependent NURF-1 and NURF-5 ISWI chromatin remodeling complexes, which form ordered nucleosome arrays on chromatin and facilitate access to DNA during DNA-templated processes such as DNA replication, transcription, and repair. The NURF-1 ISWI chromatin remodeling complex has a lower ATP hydrolysis rate than the NURF-5 ISWI chromatin remodeling complex. Within the NURF-1 ISWI chromatin-remodeling complex, binds to the promoters of En1 and En2 to positively regulate their expression and promote brain development. Histone-binding protein which binds to H3 tails trimethylated on 'Lys-4' (H3K4me3), which mark transcription start sites of active genes. Binds to histone H3 tails dimethylated on 'Lys-4' (H3K4Me2) to a lesser extent. May also regulate transcription through direct binding to DNA or transcription factors.
Synonyms: FAC1; FALZ; NURF301; NEDDFL
Tractability: Small molecule: a structure with a bound ligand is known; a high-quality ligand is known; it has a high-quality binding pocket. PROTAC: UniProt records ubiquitination sites on it; ubiquitination databases record sites on it; its protein half-life has been measured; a small molecule that binds it is known.
Target class: Epigenetic regulator; Bromodomain; Reader
Chemical probes: BI-7190 (high quality), NVS-BPTF-1 (high quality), TP-238 (high quality)
Gene: Protein-coding gene on chromosome 17 (67,825,503 to 67,984,378, forward strand). Ensembl gene ENSG00000171634.
Subcellular location: Cytoplasm; Nucleus
Subcellular location (Human Protein Atlas): Nucleoplasm; Cytosol
Gene Ontology:
Molecular function: ATP-dependent activity, acting on DNA; protein binding; sequence-specific DNA binding
Biological process: brain development; chromatin remodeling; negative regulation of transcription by RNA polymerase II; positive regulation of transcription by RNA polymerase II; regulation of DNA-templated transcription; regulation of transcription by RNA polymerase II; cellular response to nerve growth factor stimulus; negative regulation of DNA-templated transcription
Cellular component: ATPase complex; chromatin; cytoplasm; cytosol; extracellular exosome; nucleoplasm; nucleus; NURF complex; cell body; dendrite; perinuclear region of cytoplasm
Genetic constraint (gnomAD): Loss-of-function variants: 16 observed, 268.98 expected, observed/expected ratio (o/e) 0.0595, 90% interval 0.039 to 0.09. The upper end of that interval is the gene's LOEUF score, 0.09, which puts it in group 1 of 6, group 1 being the genes least tolerant of losing a copy. Missense variants: 2,555 observed, 3,364.1 expected, observed/expected ratio (o/e) 0.76, 90% interval 0.73 to 0.79. Synonymous variants: 1,139 observed, 1,198.5 expected, observed/expected ratio (o/e) 0.95, 90% interval 0.9 to 1.
Gene-disease validity (ClinGen):
ClinGen rates the evidence that BPTF causes each of these diseases.
syndromic intellectual disability (autosomal dominant): Definitive. A intellectual disability that is part of a larger syndrome.
Homologues: Orthologues: chimpanzee BPTF (99% identical), macaque BPTF (98% identical), dog BPTF (92% identical), pig BPTF (85% identical), rabbit BPTF (85% identical), guinea pig BPTF (83% identical), rat Bptf (83% identical), mouse Bptf (83% identical), tropical clawed frog bptf (58% identical), zebrafish bptf (53% identical), Drosophila melanogaster E(bx) (26% identical). Paralogues in human: BAZ2B (10% identical), BAZ2A (9% identical), KAT2A (8% identical), KAT2B (8% identical), BAZ1B (7% identical), BAZ1A (7% identical), BRD4 (6% identical), CECR2 (5% identical), BRD2 (5% identical), BRD3 (5% identical), BRDT (5% identical).
Diseases named in the same sentence as BPTF in open-access papers:
BPTF is named in the same sentence as 72 diseases in open-access papers, as found by Europe PMC text mining. Sharing a sentence is not in itself a finding about the gene and the disease. The quoted sentences say what the papers report.
breast carcinoma (20 papers, 2014 to 2025). "High BPTF copy number is significantly associated with advanced tumor grade in ER+ and TN breast cancers." (PMID 41278204, 2025). "Another documented ISWI subfamily member implicated in breast cancer progression is the NURF complex with BPTF and RBBP4/7 subunits." (PMID 41278204, 2025). "Knockout of BPTF in mouse breast cancer models promotes the expression of immunoproteasome subunits Psmb8 and Psmb9 and antigen transporters Tap1 and Tap2, therefore resulting in enhanced antigenicity and T-cell cytotoxicity." (PMID 41278204, 2025). "Since BPTF is known to be frequently altered in breast cancer, inhibition of the BPTF bromodomain by aryl urea-1 (AU1) is a promising strategy to target the NURF1/5 remodeling complex." (PMID 41278204, 2025). "In breast cancer cell lines, BPTF can also inhibit the antitumor activity of NK cells by reducing the cell surface heparan sulfate proteoglycan and natural cytotoxicity receptor co-ligand abundance." (PMID 41278204, 2025). "In the current work, we initially sought to employ AU1 as a pharmacological inhibitor of BPTF in a continued effort to determine how NURF impacts the sensitivity of breast cancer to several different chemotherapeutic agents." (PMID 39518898, 2024). "The BPTF gene is localized to 17q24, a region reported to be amplified in breast cancer and with copy number gains observed in other solid tumors." (PMID 36530982, 2022). "Analysis of TCGA samples corroborated the BPTF copy number gain observed in breast cancer samples, including 41.2% of TNBC and 32.8% of ER-positive cases." (PMID 36530982, 2022). "BPTF copy number gain and amplification were also observed in The Cancer Genome Atlas (TCGA) breast cancer cohort." (PMID 36530982, 2022). "In this study, we report the functional and biological significance of BPTF in distinct breast cancer subtypes." (PMID 36530982, 2022). "The current studies are consistent with these findings and emphasize BPTF’s important role in breast cancer progression." (PMID 36530982, 2022). "BPTF copy number was gained in 34.1% and separately amplified in 8.2% of a breast cancer tissue cohort." (PMID 36530982, 2022). "Our results are consistent with recent studies assigning a biological role to BPTF in various solid tumors, including a pro-invasive role in breast cancer." (PMID 36530982, 2022). "To understand the mechanism by which BPTF promotes breast cancer progression, we investigated the effects of modulating BPTF expression on the PI3K pathway." (PMID 36530982, 2022). "The effects of regulating BPTF expression were examined on key oncogenic signaling pathways and on breast cancer cell proliferation, apoptosis, and cell cycle progression, as well as in xenograft models." (PMID 36530982, 2022). "We report substantial copy number gain of BPTF, assess the functional consequences of BPTF gene silencing in distinct subtypes of breast cancer, and explore the therapeutic consequences of bromodomain inhibition in vivo." (PMID 36530982, 2022). "Given the presence of copy number gains of 17q in human breast cancer, we assessed BPTF copy number using a previously developed assay in a tissue microarray cohort (N=85) of primary breast cancer specimens." (PMID 36530982, 2022). "BPTF expression was regulated in breast cancer cells by shRNA/siRNA-mediated gene silencing and BPTF cDNA overexpression." (PMID 36530982, 2022). "In BPTF knockout mouse models of breast cancer and melanoma, BPTF depletion enhances antigen processing and CD8+ T cell cytotoxicity." (PMID 34736517, 2021). "Deletion of BPTF activates a stimulatory molecule and inhibits an inhibitory antigen on the surface of mouse breast cancer and skin melanoma cells, inducing a T-cell mediated immune response." (PMID 34736517, 2021).
breast carcinoma (continued). "Using syngeneic BALB/c mouse breast cancer models, we show that the chromatin remodeling subunit bromodomain PHD finger transcription factor (BPTF) suppresses natural killer (NK) cell antitumor activity in the tumor microenvironment (TME)." (PMID 28969075, 2017). "Furthermore, inhibition of heparanase expression in breast cancer cells via knockdown of the bromodomain PHD finger transcription factor (BPTF), a known activator of heparanase expression, enhanced antitumor NK cell-mediated cytolytic activity in the TME." (PMID 40519272, 2025). "Interestingly, knockdown (KD) of BPTF in breast cancer cells leads to a reduction in heparanase (HPSE) expression, thereby compromising HPSE’s ability to cleave heparan sulfate proteoglycans (HSPGs), which serve as NCR ligands on the surface of tumor cells." (PMID 39935175, 2025). "Targeting PHF6/BPTF is effective in breast cancer mouse models." (PMID 36967443, 2023). "Finally, we aimed to develop a targeted therapeutic approach for breast cancer using the bromodomain inhibitor bromosporine, which has demonstrated affinity for BPTF." (PMID 36530982, 2022). "However, to date, the precise role played by BPTF in breast cancer progression is incompletely understood." (PMID 36530982, 2022). "In this study, we assess the biological role of BPTF in human breast cancer." (PMID 36530982, 2022). "Similarly, a recent study demonstrated that BPTF targeting can sensitize breast cancer cells to treatment with topoisomerase inhibitors." (PMID 36530982, 2022). "Moreover, RBBP4 or RBBP7 and BPTF possess high frequency of abnormal copy number in angiosarcoma, breast cancer, pancreatic cancer, prostate cancer and gastric cancer, and are mutated in colorectal adenocarcinoma, lymphoma, melanoma, etc.." (PMID 34736517, 2021). "BPTF also stimulates heparanase expression, which reduces cell surface heparan sulfate proteoglycan and natural cytotoxicity receptor co-ligand abundance, therefore inhibiting NK cell antitumor activity in breast cancer cell lines." (PMID 34736517, 2021). "Furthermore, gene expression data from human breast cancer tumors shows that elevated BPTF expression correlates with reduced antitumor immune cell signatures, supporting conserved roles for BPTF in suppressing antitumor immunity." (PMID 28969075, 2017). "In breast cancer, the BPTF/NURF complex may promote the immune escape of cancer cells." (PMID 41278204, 2025). "In addition, targeting PHF6/BPTF creates an epigenetic vulnerability for breast cancer treatment." (PMID 36967443, 2023). "Moreover, NFκB is another transcription factor associated with the expression of several ABC-transporters, especially in breast cancer, which might require BPTF for its transcriptional activity." (PMID 35326669, 2022). "In breast cancer, PHF6 recruits the chromatin-remodeling factor BPTF for epigenetic modifications, thereby enhancing the transcriptional activity of the HIF pathway, which in turn promotes tumor angiogenesis and metabolic reprogramming." (PMID 41515604, 2025). "In breast cancer cells, BAP18 interacts with the BPTF-SMARCA1 complex to facilitate CTCF recruitment to ERα, thereby promoting promoter-enhancer looping and ERα target gene expression." (PMID 41381516, 2025). "These genes included BPTF, PHF5A, and SPG7 in cancer of female genital organs, as well as FGF10, NFIX, and SCAP in breast cancer." (PMID 38409266, 2024). "Stable shRNA-mediated silencing of BPTF significantly inhibited cell proliferation and induced apoptosis in TNBC and ER-positive human breast cancer cell lines." (PMID 36530982, 2022). "Conversely, BPTF cDNA overexpression in TNBC and ER-positive breast cancer cells enhanced breast cancer cell proliferation and reduced apoptosis." (PMID 36530982, 2022). "We then assessed the consequences of regulation of BPTF expression on the PI3K signaling pathway, which is of particular significance to breast cancer progression." (PMID 36530982, 2022).
breast carcinoma (continued). "As a result of these observations, we focused our attention on the functional effects of BPTF on the progression of TNBC and ER-positive human breast cancer subtypes." (PMID 36530982, 2022). "We have fully validated the epigenetic screens in vivo and in vitro by analyzing four different hits and we have demonstrated that BAZ1B, BPTF, BRD4 and CHD4 are essential for breast cancer growth." (PMID 27779108, 2016). "Given that PHF6 recruits BPTF to sustain HIF transcriptional activity, we thus wondered whether targeting BPTF using specific inhibitor (AU1) could suppress breast cancer progression." (PMID 36967443, 2023). "Moreover, further research will evaluate whether the BPTF-specific PROTAC degrader could enhance NK cell-mediated antitumor efficacy against other malignancies with significant BPTF overexpression, such as lung cancer and breast cancer." (PMID 39935175, 2025). "We also identified the transcription factor BPTF, known for its role in chromatin remodeling and mammary stem cell renewal and differentiation, that is highly amplified in many cancer types and significantly positively correlated to MFS in breast cancer patients irrespective of the subtype." (PMID 31278301, 2019).
melanoma (16 papers, 2015 to 2025). A malignant, usually aggressive tumor composed of atypical, neoplastic melanocytes. "In contrast, the silencing of BPTF reduces the proliferative capacity and metastatic potential of melanoma cells." (PMID 40554927, 2025). "Studies have reported that BPTF overexpression can predict poor prognosis in various malignant tumors, such as melanoma, colon cancer and non-small-cell-type lung cancer." (PMID 37170211, 2023). "We previously reported a pro-oncogenic role for BPTF in melanoma by virtue of its modulation of the MAP kinase pathway as well as its promotion of resistance to targeted therapy." (PMID 36530982, 2022). "For example, BPTF gene copy number is frequently amplified in human tumors, particularly in melanoma, neuroblastomas and lung cancers." (PMID 34736517, 2021). "In a cultured melanoma cell line, BPTF suppressed proliferative capacity and significantly reduced metastases upon intravenous injection in nude mice." (PMID 30558204, 2018). "ShRNA-mediated silencing of the NURF subunit BPTF revealed its essential role in several melanoma cell lines and in untransformed melanocytes in vitro." (PMID 26440048, 2015). "While BRG1 and BPTF are essential in melanocytes and melanoma cells in vitro, they regulate overlapping but distinct gene expression programs." (PMID 26440048, 2015). "The essential role of BPTF in melanoma and melanocyte cells in vitro prompted us to investigate its role in the murine melanocyte lineage in vivo." (PMID 26440048, 2015). "More importantly, they showed that BPTF expression is increased in human melanomas, where the corresponding gene is often amplified and that these increases are predictive of poor outcome." (PMID 26440048, 2015). "Furthermore, we found that the synergistic effect of BRG1 and BPTF is required for maintaining hub gene set expressions in melanoma cells." (PMID 36967443, 2023). "In addition, we showed that BPTF transduces certain key pro-proliferative effects mediated by the transcription factor MITF in melanoma." (PMID 36530982, 2022). "We previously reported BPTF copy number gain in primary melanoma, along with a prognostic role." (PMID 36530982, 2022). "Moreover, BPTF possess both high frequency of mutation and abnormal copy number in angiosarcoma, COAD, ESCA, LIHC, LUAD, melanoma and urothelial carcinoma." (PMID 34736517, 2021). "Furthermore, the bromodomain PHD finger transcription factor (BPTF) is amplified and overexpressed in melanomas, and BPTF is required for c-MYC transcriptional activity and in vivo tumorigenesis." (PMID 28055972, 2017). "Decreases in heparanase levels could also contribute to defects in metastases, as previously observed with BPTF KD melanoma tumors." (PMID 28969075, 2017). "BPTF is selectively required in melanoma cells and melanocytes in vitro." (PMID 26440048, 2015). "Acting as a cofactor for MITF is therefore only one facet of BPTF function in melanoma cells." (PMID 26440048, 2015). "However, in a different melanoma line, increased BPTF expression induced cell proliferation." (PMID 30558204, 2018). "BPTF is a target and regulator of MYC and exerts pro-tumourigenic functions in diverse cancers including melanoma, hepatocellular carcinoma, or ovarian cancer." (PMID 40633141, 2025). "In human melanoma models, targeting the SWI/SNF complex subunit (BRG1) and the NURF scaffolding subunit (BPTF) both inhibited tumor proliferation." (PMID 36967443, 2023). "We next interrogated transcriptome data to assess expression of the BPTF, SMARCA1 and SMARCA5 subunits of NURF in a collection of human melanoma cells." (PMID 26440048, 2015). "In melanoma MNT1 cells, shBPTF silencing led to a spindle-like bipolar morphology, while in 888-Mel cells, BPTF knockdown led to strongly reduced cell numbers with the remaining cells again showing a spindle-like bipolar morphology." (PMID 26440048, 2015).
melanoma (continued). "For instance, the overexpression of Bromodomain PHD Finger Transcription Factor (BPTF), a subunit of the NURF chromatin remodeling complex, is reported to foster the proliferation of melanoma cells, as well as predict a poor prognosis in melanoma patients." (PMID 40554927, 2025). "We found BPTF significantly promoted cell proliferation mainly by regulating the MAPK and PI3K-AKT pathways, which was similar to the report in melanoma but different from the report that BPTF promoted cell development and differentiation through TGF-Smad pathway." (PMID 26418899, 2015). "Similarly, MITF and BPTF co-repress SASP genes like SERPINE1, IL24, PDGFB, and CYR61 as well as ZEB1 that has a crucial role in melanoma progression." (PMID 26440048, 2015). "While these observations identified BPTF as a prognostic factor for melanoma progression, they did not provide a molecular basis for BPTF function in melanoma." (PMID 26440048, 2015). "We show here that BPTF acts as a cofactor for MITF in regulating critical cell cycle, invasion, motility and apoptosis genes thus providing a molecular mechanism by which BPTF promotes melanoma growth and progression." (PMID 26440048, 2015). "There is therefore no general requirement for BPTF for proliferation, but rather a specific requirement in melanoma cells that is both MITF-dependent and independent." (PMID 26440048, 2015). "Nevertheless, BPTF likely acts as a cofactor for other transcription factors in MITF-negative melanoma cells and there are clearly genes regulated by BPTF, but not MITF, in MITF-expressing lines." (PMID 26440048, 2015). "Bromodomain PHD finger transcription factor (BPTF) promotes melanoma development by regulating B-cell lymphoma-2 (BCL2) anti-apoptosis, influencing melanocyte stem cell differentiation, and affecting melanoma proliferation via extracellular signal-regulated kinases regulation." (PMID 41479783, 2025). "Moreover, as BPTF is essential in 1205Lu cells, it may have both MITF-dependent and independent functions in melanoma." (PMID 26440048, 2015).